FGF21 (fibroblast growth factor 21)
Diseases named in the same sentence as FGF21 in open-access papers (continued):
Sharing a sentence is not in itself a finding about the gene and the disease.
metabolic disease (338 papers, 2010 to 2026). A congenital disorder (due to inherited enzyme abnormality) or acquired (due to failure of a metabolically important organ) disorder resulting from an abnormal metabolic process. "It is widely believed that the mechanism by which FGF21 improves metabolic disorders is associated with its unique protein-protein interaction and crosstalk with peroxisome proliferator-activated receptor." (PMID 40756666, 2025). "FGF-21 is a hormone that regulates glucose and lipid metabolism, and higher levels are often associated with metabolic diseases." (PMID 38318571, 2024). "Due to the fact that kidney transplant recipients are at the increased risk of metabolic disorders we wanted to analyze the factors related to plasma FGF21 concentration in patients long time after kidney transplantation." (PMID 39064306, 2024). "In this work, we first established that the minor allele at rs838133 mimics the alterations in FGF21 seen in metabolic diseases." (PMID 34141520, 2021). "In view of the strikingly overlapping functions between FGF21 and adiponectin, the underlying role of the FGF21-adiponectin pathway in metabolic disorders has become a research hotspot." (PMID 34321008, 2021). "In total, the rs838133 minor (A) allele is associated with higher hepatic FGF21 protein levels in healthy controls and in patients with metabolic disease (MAFLD), though its impact is more profound in the latter." (PMID 34141520, 2021). "Loss of FGF21 worsens metabolic disorder and contributes to aberrant molecular events, including lipid metabolism, in HCC development." (PMID 32363190, 2020). "Dysregulation of endocrine FGF signaling, particularly FGF19 and FGF21, has been implicated in metabolic disease, suggesting their potential as therapeutic mechanisms." (PMID 33381084, 2020). "The collective findings indicate that FGF21 has a mitohormetic effect in response to various metabolic disorders that are positively associated with mitochondrial dysfunction in adaptive thermogenesis." (PMID 31570705, 2019). "FGF21 is a hormone in the FGF superfamily that exerts several beneficial effects on metabolic diseases and their associated complications." (PMID 31511499, 2019). "FGF21 is a hormone that mediates a number of beneficial effects relevant to metabolic disorders and their associated complications." (PMID 31511499, 2019). "Since the function of FGF19 and FGF21 is dependent on β-klotho as a co-receptor; decreased expression of β-klotho causes metabolic disorders." (PMID 31151464, 2019). "This study is the first, to our knowledge, to establish the critical role of FGF21 in the salutary effects of CO on metabolic disorders, using mice genetically deficient in FGF21." (PMID 29295856, 2018). "The importance of FGF-21 as a potential therapeutic agent and a diagnostic biomarker for metabolic diseases is increasingly being realized." (PMID 30298107, 2018). "Together, these data support a role for increased DNA methylation of FGF21 in the regulation of adipose FGF21 expression in association with metabolic disease." (PMID 29091029, 2017). "FGF21 is a hormone involved in glucose and lipid homeostasis, and high levels of FGF21 seem to be associated with metabolic disease." (PMID 26199742, 2015). "Fgf21 single polymorphisms are possibly related with metabolic diseases and FGF21 and biomarker of metabolic diseases." (PMID 25071723, 2014). "Individuals with a cluster of metabolic disorders have increased serum FGF21 level, and research has implicated the up-regulation of this cytokine as acting to compensate for the abnormal metabolic status." (PMID 23981342, 2013). "In conclusion, our new data with LY, an engineered FGF21 variant, support further exploration of FGF21-based therapies for the treatment of metabolic disorders, including studies in patients at the advanced stages of disease development." (PMID 23823755, 2013).
metabolic disease (continued). "As FGF21 analogues and mimetics are currently in clinical trials for the treatment of various metabolic disorders such as metabolic syndrome‐associated steatohepatitis (MASH), this may open novel opportunities to modulate cancer metabolism." (PMID 41131959, 2026). "Thus, the results also provide a crucial foundation for developing novel, hyper-stable FGF21 variants with enhanced biological activities for treating metabolic diseases through structure-based protein engineering." (PMID 39884432, 2025). "Moreover, FGF21 serves as a diagnostic biomarker in metabolic diseases related to glucose and lipid metabolism, with elevated serum FGF21 levels observed in early-stage NAFLD patients." (PMID 40786047, 2025). "The clinical significance of FGF21 in humans remains unclear due to a lack of understanding about the causes and consequences of higher circulating FGF21 levels in metabolic disorders." (PMID 39640300, 2024). "Although the FGF21 test is not a routine and standard test in hospital laboratories, current studies have observed that FGF21 is upregulated in metabolic and other disorders and realized its potential value as a diagnostic and prognostic biomarker for metabolic diseases." (PMID 36594101, 2023). "The association between FGF-21 and T2DM and its related metabolic diseases indicated that FGF-21 may be a promising biomarker and antidiabetic target, which has attracted the attention of researchers." (PMID 37658393, 2023). "Since chronic high levels of blood FGF21 are a risk factor for several metabolic diseases, it is necessary to evaluate whether insulin dose simply affects FGF21 secretion and/or FGF21-related metabolic diseases." (PMID 35192641, 2022). "Because FGF21 can regulate metabolism and cellular aging simultaneously, FGF21 analogs and FGF21 receptor agonists are gradually being valued and could become a treatment approach for aging-associated metabolic diseases." (PMID 33869312, 2021). "Thus, the association between FGF21, energy metabolic diseases, and aging has recently attracted increasing attention." (PMID 33869312, 2021). "Thus, to provide a comprehensive evaluation of the basis of FGF21 abnormalities in metabolic disease, we analyzed the association between rs838133 and the expression of molecular actors of FGF21 responsiveness (FGFRs and KLB) in liver and adipose tissue." (PMID 34141520, 2021). "GDF15 and FGF21 are endocrine factors associated with liver and metabolic diseases." (PMID 32179785, 2020). "The role of FGF21 in the development of metabolic disease caused by fructose consumption may differ based on biological sex." (PMID 31687174, 2019). "The elevated FGF21 levels observed in these patients could be due to a high FGF21 synthesis by the tumor cells or the stress caused microenvironment metabolic disorders." (PMID 27358750, 2016). "In addition, Fgf21 polymorphisms are possibly related with metabolic diseases and FGF21 are biomarker of metabolic diseases." (PMID 25071723, 2014). "A 5 kg/m2 increase in BMI may correspond to approximately twofold increase in serum FGF21 levels, as calculated by the regression equation, suggesting that the chronic high level of blood FGF21 may have adverse effects on metabolic disease risk, as seen in healthy subjects." (PMID 35192641, 2022). "This change may indicate increased risk for development of metabolic disease or liver injury in women, or it could be the case that decreased baseline FGF21 levels down‐regulate sweet preference in an effort to prevent ongoing excessive fructose consumption and metabolic sequelae." (PMID 31687174, 2019). "The circulating FGF21 level is closely related to many metabolic disorders and is a potential biomarker for many disease." (PMID 40005931, 2025). "Under metabolic disorders, FGF21 expression is paradoxically elevated in circulation but often accompanied by FGF21 resistance, characterized by impaired signaling in target tissues." (PMID 41305665, 2025).
metabolic disease (continued). "Currently, FGF-21 analogs are being developed for use in the treatment of metabolic diseases such as diabetes, NAFLD and heart failure." (PMID 40648864, 2025). "By combining biophysical characterization techniques with biochemical methods, these new findings expand our understanding of FGF21’s impact on mitochondrial functions and its involvement in treating metabolic diseases." (PMID 39884432, 2025). "Our results reinforce the utility of FGF21 as a biomarker, as its serum levels were found to rise in direct relation to the severity of metabolic disorders." (PMID 40559404, 2025). "FGF21 increases glucose uptake by cells, promotes fatty acid oxidation, reduces blood glucose levels, and alleviates metabolic diseases." (PMID 39884432, 2025). "This highlights the dual role of FGF-21 as a compensatory mechanism in early metabolic stress and a therapeutic target for advanced metabolic disorders." (PMID 40437610, 2025). "In this context, not only should the expression of Fgf21 be considered in the study of metabolic diseases, but also its sensitivity and receptor complex." (PMID 41373837, 2025). "Fibroblast growth factor 21 (FGF21) is involved in various metabolic disorders and neurodegenerative diseases." (PMID 40172524, 2025). "In murine models of mitochondrial stress, the upregulation of FGF21 serves as a protective mechanism against mitochondrial damage and metabolic disorders." (PMID 40881124, 2025). "We also observed up‐regulation of FGF2, 13 and 14 in patients with increased FGF21 expression, and this broadens the perspective of FGFs in metabolic disorders." (PMID 39962359, 2025). "The increase in serum FGF21 serves as a protective response to liver lipotoxicity, enhancing fatty acid β-oxidation and reducing lipogenesis to improve liver function in these metabolic diseases." (PMID 39884432, 2025). "Previous studies indicate that FGF21 expression and circulating levels exhibit stage-dependent changes during metabolic disease progression." (PMID 41305665, 2025). "On the other hand, due to metabolic disorders and reduced sensitivity to FGF21, the liver must compensatorily synthesize and secrete more FGF21 to maintain metabolic homeostasis." (PMID 39819596, 2025). "The results of this study provide valuable insights for the development of potent FGF21-based therapeutic agents to combat dilapidating metabolic diseases." (PMID 39884432, 2025). "Recent meta-analyses have suggested that chronic exercise reduces circulating FGF21 levels in adults with metabolic disorders, potentially reflecting improved FGF21 sensitivity and metabolic health." (PMID 40869331, 2025). "Addressing these challenges through multidisciplinary approaches will be essential to translate FGF21-based therapies from bench to bedside, ultimately realizing their potential to revolutionize treatment paradigms for metabolic diseases." (PMID 40881124, 2025). "FGF-21 expression or analogs counteract metabolic disorders, inflammation and fibrosis in the liver, while FGF-21 can have oncogenic activity in various cancers." (PMID 39263327, 2024). "In particular, adiponectin and FGF21, which are induced by fasting or caloric restriction, have diverse roles in various tissues controlling metabolic diseases, as well as in delaying aging and promoting longevity." (PMID 38672227, 2024). "These properties make FGF21 a molecule of interest for treating metabolic diseases such as obesity, dyslipidemia, or insulin intolerance." (PMID 38379823, 2024). "Overall, the efficacy of FGF21 in the treatment of metabolic disorders needs to be validated in large, multi-center trials in the future." (PMID 39409124, 2024). "FGF21 levels increase with age and have been proposed as a protective factor against age‐related metabolic diseases." (PMID 39239870, 2024). "Currently, metabolic diseases are prevalent worldwide, underscoring the significant market potential of FGF21." (PMID 38867280, 2024).
metabolic disease (continued). "Aging mice lacking FGF21 spontaneously develop fatty liver and inflammatory response of lung under healthy feeding environment, indicating the critical role of FGF21 in aging-related metabolic disorder and inflammation." (PMID 38653921, 2024). "To further confirm the role of liver FGF21 signaling in the improvement of metabolic disorders induced by a KD, we generated liver KLB knockdown mice using AAV injection." (PMID 38609395, 2024). "Many researches evidenced that FGF-21 regulates glucose-lipid metabolism has made it a promising therapeutic target for metabolic disease." (PMID 38755663, 2024). "Experimental findings suggest that higher concentrations of FGF21 attenuate acute metabolic disorders, contributing to extended lifespan." (PMID 39302236, 2024). "One mechanistic target that has been identified for treating MASLD is fibroblast growth factor 21 (FGF-21), which is involved in ferroptosis, a process that in the liver has recently gained attention due to its implications in metabolic disease." (PMID 39411175, 2024). "FGF21, induced by factors such as diet, exercise, cold exposure, and metabolic disorders, is significantly upregulated in diabetic environments." (PMID 38312833, 2024). "Compared with natural FGF21, FGF21 analogs have become drug candidates for the treatment of cardiovascular and metabolic diseases owing to their long half-life and greater stability in vitro." (PMID 39144082, 2024). "In fact, it appears that chronic trygliceride accumulation in the liver creates a stress condition that damages hepatocytes, leading to increased transcription and secretion of FGF21, suggesting it as a potential biomarker for metabolic disorders." (PMID 39409124, 2024). "The positive role of FGF21 against inflammatory progression and metabolic disorder has been demonstrated in previous study." (PMID 38653921, 2024). "Fibroblast growth factor 21 (FGF21) was reported to be protective against inflammation in metabolic disease in recent studies." (PMID 37864659, 2024). "In this observational study, we analysed a group of subjects with metabolic disorders to unravel the putative link between visceral adiposity and FGF-21 serum levels." (PMID 37409233, 2023). "Clinical studies have shown that the circulating FGF-21 level was closely related to metabolic diseases." (PMID 37070097, 2023). "In patients with CAD, serum FGF21 concentrations are elevated in comparison with healthy subjects and the effect is more pronounced with additional metabolic disorders, such as T2D." (PMID 36905198, 2023). "Its capability to improve the metabolic profile of obese subjects has increased interest in FGF21 as a therapeutic agent against metabolic diseases." (PMID 37355753, 2023). "Here, we aimed to unveil the mechanisms underlying the protective effects of FGF21 on NASH using APOE*3-Leiden.CETP mice, a well-established model for human-like metabolic diseases." (PMID 36648330, 2023). "The finding that FGF21 regulates glucose–lipid metabolism has made it a promising therapeutic target for metabolic disease." (PMID 36836789, 2023). "Intensive research uncovered that systemic administration of high doses of FGF21 strongly prevents or treats metabolic diseases." (PMID 37755259, 2023). "FGF21 is an important regulator of energy homeostasis and a potential therapeutic target for metabolic diseases." (PMID 36742397, 2023). "The impact of chronic exercise on circulating levels of FGF21 in individuals with metabolic disorders has been investigated in various studies, and the results appear to be conflicting." (PMID 37755259, 2023). "By mediating AMP-related pathways, FGF-21 has a positive effect on the progression of cardiovascular diseases and other metabolic disorders." (PMID 37239098, 2023).
metabolic disease (continued). "Although FGF21 was proven to play a beneficial effect on the healthy via its lipid-lowing, anti-oxidant, and anti-inflammatory properties, the circulating concentration of FGF21 is increased in various metabolic diseases." (PMID 37009852, 2023). "Our results showed that the mice receiving FGF21 injection showed a region‐specific recovery from PD‐induced brain metabolic disorders, especially in the midbrain, striatum, and cortex." (PMID 37334756, 2023). "Further research is needed to investigate the mechanism of FGF21 on the development and progression of metabolic disorders in these T2DM individuals with HP." (PMID 37424900, 2023). "As a hormone, FGF21 regulates glucose–lipid metabolism and is becoming a promising therapeutic target for metabolic disease." (PMID 36836789, 2023). "In summary, FGF21 is a valuable biomarker for metabolic diseases and deserves further study to translate the biomarker potential into clinical laboratories." (PMID 36594101, 2023). "In this systematic review and meta-analysis, we evaluated the effects of FGF21 analogs as a treatment for metabolic disorders." (PMID 37948566, 2023). "On the other hand, exogenous supplementation with FGF21 has also been proven to be effective in relieving metabolic disorders." (PMID 37576954, 2023). "Owing to this, the pathophysiology and potential pharmacological role of FGF21 in metabolic disease have been studied extensively." (PMID 36028609, 2023). "On the one hand, FGF21 can be used as a biomarker to predict the occurrence and prognosis of metabolic disorders in the early stage." (PMID 37576954, 2023). "Further studies are warranted in cats with more severe metabolic disease to determine if FGF21 treatment indeed lacks influence on this species." (PMID 36756310, 2023). "Given the promising therapeutic potential of FGF21 in metabolic diseases, gene therapy and many FGF21 analogs have been developed." (PMID 35909571, 2022). "Many of the effects of a KD on metabolic disorders are mediated by PPARα-dependent fibroblast growth factor 21 (FGF21)." (PMID 35215432, 2022). "During the last decades, the pleiotropic beneficial actions of FGF21 on metabolic disorders in animals promoted FGF21-based drugs for therapeutic purposes." (PMID 36618930, 2022). "One study proved that FGF21 produced by myocardial cells functions as an autocrine factor to attenuate metabolic disorder, prevent hypertrophy, and activate proinflammatory pathways in cardiac tissue." (PMID 35677107, 2022). "Administrating of FGF21 analogs and mimetics has demonstrated therapeutic benefit in human and rodent models of metabolic diseases, but still more studies and clinical trials will be required to prove the efficacy of these treatments." (PMID 36457562, 2022). "Fibroblast growthfactor 21 (FGF21) is a liver-secreted hormone with several beneficial effects onobesity-related metabolic disorders." (PMID 39077619, 2022). "FGF21, a master regulator for metabolic homeostasis, is focused on the treatment of metabolic disorders." (PMID 36235573, 2022). "Based on these studies, FGF-21 was considered an ideal medicine for the treatment of metabolic diseases." (PMID 36238554, 2022). "The peripheral metabolic effects of FGF-21, FGF-21-based drug development, and translational research on metabolic diseases are the major topics in this field." (PMID 36238554, 2022). "Elevated serum FGF21 levels are considered a compensatory response in the early stages of various metabolic diseases." (PMID 35677107, 2022). "More importantly, FGF21-based drugs are explored to ameliorate metabolic diseases because of their crucial actions in regulating systemic glucose and lipid metabolism." (PMID 36618930, 2022). "These previous studies suggest that it is necessary to distinguish between beneficial FGF21 effects and the resistant state, and the determinant factors of circulating FGF21 have important implications for metabolic disease prediction and prevention." (PMID 35192641, 2022).